CD68 (CD68 molecule)
Diseases named in the same sentence as CD68 in open-access papers (continued):
Sharing a sentence is not in itself a finding about the gene and the disease.
squamous cell carcinoma (15 papers, 2011 to 2024). A carcinoma arising from squamous epithelial cells. "Our study evaluated the immunoexpression of CD3, CD8, CD20 and CD68 at different stages of lip cancer and Squamous Cell Carcinoma progression." (PMID 38219446, 2023). "During radiotherapy, the proportions of MDSCs were clearly increased in adenocarcinoma patients and the percentages of CD68+CD163+M2-like macrophages were markedly elevated in squamous carcinoma patients." (PMID 35928634, 2022). "To better understand the involvement of HPV oncoproteins in CD68+ macrophage recruitment to the tumor, we developed an orthotopic female mouse model injected with squamous cell carcinoma cell lines transfected with HPV16-E6, −E7 or –E6/E7." (PMID 29541395, 2018). "Intraepithelial tumor infiltrating lymphocytes: CD8+, CD4+, FOXP3+, CD56+, tumor associated macrophages: CD68+, and GZB+ cells were calculated in 85 vulvar squamous cell carcinomas with previously defined p16Ink4a and high-risk HPV-status." (PMID 28515351, 2017). "All tumour samples for squamous cell carcinoma and adenocarcinoma expressed CD68 (alveolar macrophages in the stroma of the tumours, and healthy lung tissue)." (PMID 21794149, 2011). "In general, the stroma of squamous cell carcinoma was characterized by a high content of CD68+ macrophages (p = 0.0343) and FOXP3+ regulatory T-cells (p = 0.0014), which indicates the distinctive properties of the microenvironment of this histological type of tumor." (PMID 32933105, 2020). "Interestingly, adenocarcinoma samples showed more CD68 staining in the tumor periphery compared to squamous-cell carcinoma, indicating an increased infiltration of TAMs (left)." (PMID 31383898, 2019). "Still, in the Lip Cancer and Squamous Cell Carcinoma, there was an increase in the amount of CD3+ (p < 0.001), CD8+ (p = 0.035), CD20+ (p < 0.001) and CD68+ (p < 0.001) cells within the tumor islands (intratumoral)." (PMID 38219446, 2023). "In peritumoral lip cancer and Squamous Cell Carcinoma, CD3+ and CD8+ cells showed a significant direct correlation (p = 0.004, r = 0.467), as well as CD68+ and CD8+ cells (p = 0.017, r = 0.390)." (PMID 38219446, 2023). "In lip cancer and Squamous Cell Carcinoma there was peritumoral increase in CD3+ (p = 0.037), CD8+ (p < 0.001), as well as CD20+ (p < 0.001) and CD68+ (p < 0.001) cells." (PMID 38219446, 2023). "In lip cancer and Squamous Cell Carcinoma the immunoexpression of CD3+ (p = 0.002, r = 0.474), CD8+ (p = 0.001, r = 0.521) and CD68+ (p = 0.030, r = 0.363) showed direct correlation between intra and peritumoral region." (PMID 38219446, 2023). "Higher densities of CD68+ and CD163+ cells were also observed in HPV+ tumors of other HPV-induced squamous cell carcinomas, such as oropharyngeal squamous cell carcinoma and cervical squamous cell carcinoma." (PMID 34194435, 2021). "By contrast, in patients with squamous cell carcinoma, neither the detectable tumor iron content nor the numbers of CD68+ TAMs affected overall patient survival." (PMID 31383898, 2019).
synovitis (15 papers, 2005 to 2025). Inflammation of a synovial membrane. "Although our univariate analysis indicated that L-006235 altered the association between pain behaviour and synovitis, this is likely mediated by a cell type other than CD68+ or CD206+ macrophages." (PMID 30706033, 2018). "Sublining CD68+ macrophage density has been shown to be similar in PsA and RA synovitis although, in a small study we found that CD68+ macrophage density was associated with erosive disease only in RA, suggesting that the destructive potential of ST CD68+ macrophages may differ between RA and PsA." (PMID 33679701, 2020). "Immunostaining revealed very low-grade residual synovitis, as demonstrated by the presence of one to three layers of CD68+ cells (resident macrophages) in the lining and few CD3+ and CD20+ cells (T and B lymphocytes, respectively)." (PMID 26842890, 2016). "There were approximately 13 % and 27 % of CD68-positive cells in low- and moderate-grade synovitis, respectively." (PMID 27044395, 2016). "Immune cells can be grouped into follicular structures (follicular synovitis, mostly B cells) in 30–40 % of patients or be randomly distributed within the sublining layer (diffuse synovitis, predominantly CD68+ cells)." (PMID 27094362, 2016). "Synovial tissue showed a higher percentage of CD68 marker in moderate compared with low-grade synovitis." (PMID 27044395, 2016). "ME of the MCP significantly correlated to sublining CD68 staining (r = 0.750, P = 0.02), the Synovitis Score (r = 0.743, P = 0.02), and the subscores for lining layer hypertrophy (r = 0.789, P = 0.01) and cellular density (r = 0.842; P = 0.004)." (PMID 25270553, 2014). "We found that overweight/obese RA patients reaching stable clinical and ultrasound remission showed higher degree of residual synovitis in terms of synovial CD68+, CD20+ and CD3+ cells whose IHC scores directly correlated with the BMI value at the time of remission achievement." (PMID 31320744, 2019). "Furthermore, to confirm that CCL3/MIP1α and S100A8 were specific markers of SM, we also immunostained serial sections of synovial tissue from patients with moderate synovitis using the positive control macrophage marker CD68." (PMID 27044395, 2016). "Synovial biopsies were stained for determination of sublining CD68 and the Synovitis Score." (PMID 25270553, 2014). "APRIL was exposed to be particularly expressed in CD83+ dendritic cells, with the maximum expression in GC synovitis, while BAFF was similarly expressed across different types of synovitis and localized to CD68+ macrophages." (PMID 40821822, 2025). "The finding that synovitis was most closely associated with colony number and area prompted us to perform immunostaining for synovitis-related and MSC mobilization-related molecules (CD68, CD73, and ZO-1)." (PMID 37679780, 2023). "Then, for in-depth analysis of the main synovial cell populations present in the synovial tissue, we analyzed CD68 and CD55 to establish the percentage of synovial macrophages and synovial fibroblasts, in both low- and moderate-grade synovitis." (PMID 27044395, 2016). "The synovitis score was slightly but not significantly higher in the Im-B group than in the Im-NS group, and CD68-positive cells were primarily observed in the synovial membrane, indicating that iron deposition potentially induces synovial inflammation." (PMID 33213419, 2020). "Overweight/obese RA in stable clinical and US remission showed higher degree of residual synovitis in terms of sublining CD68+, CD20+ cells and lining and sublining CD3+ compared to normal weight RA." (PMID 31320744, 2019). "Apart from a difference in CD68+ macrophages and the somewhat unexpected presence of PMCs in PsA synovitis, no major differences in infiltrating cell populations were described between PsA and RA." (PMID 15899044, 2005).
synovitis (continued). "In addition, the density of subintimal common mononuclear inflammatory cell types, including CD68+ cells, CD3+ cells, CD38+ cells, CD20+ cells, and CD79a+ cells, were significantly higher in high-grade synovitis RA patients than that in low-grade synovitis RA patients." (PMID 22656185, 2012).
liver cancer (14 papers, 2015 to 2025). An epithelial or non-epithelial malignant neoplasm that arises from the liver. "The presence of CD68-positive cells within the liver cancer cell lines was particularly intriguing, as CD68 is known as a marker for cancer-associated macrophages (CAMs) but is also present in other liver-associated cell types, like hepatocytes." (PMID 38201286, 2023). "CD68 is the marker of macrophages and elevated levels of CD68 were significantly related to poor overall survival in liver cancer." (PMID 38223688, 2023). "Specific platelet activation, governed by the macrophages in the liver, CD68+ Kupffer cells, was described to be functionally involved in chronic liver inflammation, chronic tissue damage, ROS production, and liver cancer formation." (PMID 33723077, 2021). "Firstly, we detected the expression level of ITGAV protein in clinical tissue samples from 5 patients with liver cancer, and found that the expression level of ITGAV in liver cancer tissues was positively correlated with the expression levels of CD68 (macrophage marker) and COL1A1 (CAFs marker)." (PMID 40018050, 2025). "A large amount of CD68 positive macrophages were found in paracarcinoma tissue and liver cancers." (PMID 35371096, 2022). "To investigate the expression of G0S2 in liver cancer tissues, we performed mIHC using antibodies against CD14, CD68, and G0S2 on an HCC tissue microarray to enable double staining with the monocyte markers." (PMID 40282408, 2025). "The results of multiplexed IF staining of 105 primary liver cancer margin areas from the validation cohort 1 (HCC, n = 53; ICC, n = 52) also revealed that macrophages (CD68+ cells) were significantly enriched in the first layer (0–250 μm) on the tumor side." (PMID 37337030, 2023). "In accordance with the Barcelona Clinic Liver Cancer staging system, 12 patients (40%) were classified as Stage B, while 18 patients (60%) were classified as Stage C. Median CD3 and CD68 counts were found to be 51.0 and 46.0 per 20,000 μm2, respectively." (PMID 37189554, 2023). "The Barcelona Clinic Liver Cancer (BCLC) stage; the microvascular invasion status; the density of TILs; the expressing levels of CD66b, OX40, and PD-L1 in the immune cell; CD68; and CD8 were the predictors of patients’ overall survival (OS)." (PMID 35936682, 2022).
bladder cancer (13 papers, 2011 to 2025). "Since many of the biomarkers in the bladder cancer-associated diagnostic panel are known immunomodulators, we assessed the bladder tumors for the presence of CD3+ cells (pan-T cell) and CD68+ cells (macrophage) as a snapshot of the tumor immune landscape." (PMID 31905599, 2019). "we systemically reviewed and analyzed the prognostic value of TAMs identified by CD68 or CD163 biomarker in bladder cancer patients." (PMID 29861872, 2018). "To address this controversy, we performed this meta-analysis based on the TAMs identified by CD68 and CD163 markers to evaluate the potential association between TAMs density and prognostic outcomes in bladder cancer." (PMID 29861872, 2018). "The median number of CD68+ macrophages was significantly elevated in bladder cancers compared with cystitis and polyps (p = 0.001, p = 0.006 respectively)." (PMID 27716046, 2016). "Previous studies have always used CD68 as a single immunohistochemical pan-Mφ marker to evaluate the location and density of Mφs and their clinical relevance in bladder cancer, but the results have been conflicting." (PMID 26001293, 2015). "However, a detailed functional analysis of CD68 and PD-1 in the context of bladder cancer requires further investigation." (PMID 34079767, 2021). "Consistent with the results obtained from the mouse model, we found that LNMAT1 expression was positively associated with the macrophage infiltration intensities of the intratumoral and peritumoral regions of bladder cancer, as indicated by the macrophage marker CD68+ (p < 0.05)." (PMID 30237493, 2018). "The increased numbers of CD3+ T lymphocytes and CD68+ macrophage in bladder cancer suggest that these cells might participate in the process of bladder cancer." (PMID 27716046, 2016). "However, pT1 bladder cancers confirmed the highest count (mean ± SD) of CD3+ T cells (983.7 ± 662.0; p = 0.022), CD8+ T cells (359.9 ± 238.0; p = 0.008) and CD68+ TAMs (181.6 ± 93.9; p = 0.014) compared to pTa bladder cancer and CIS." (PMID 27221038, 2016). "Current study is the first systemic review and meta-analysis to evaluate the prognostic value of CD68+ and CD163+ TAMs in bladder cancer." (PMID 29861872, 2018). "While BMP4 has been shown to induce M2-polarization of macrophages in bladder cancer, we did not observe significant differences in CD68+ or CD163+ macrophage levels between BMP4low and -high PDAC (TC: p = 0.85; TF: p = 0.52)." (PMID 40826447, 2025). "Moreover, immunofluorescence performed on bladder cancer tissue samples revealed that samples with high IGF2BP2 expression exhibited relatively high levels of CD14 and CD68, consistent with the TCGA‐BLCA and spatial transcriptomics findings." (PMID 39711402, 2024). "CD274 (PDL-1), CD68, CD16, and CD3 expression were observed in the bladder cancer tissues." (PMID 36732736, 2023). "While TAMs only identified with CD68 marker in bladder cancer samples were not significantly correlated with the prognostic outcomes and clinicopathological parameters in bladder patients." (PMID 29861872, 2018). "Subgroup analyses involved with Bacillus Calmette Guerin (BCG) treatment or sample locations either showed that CD68+ TAMs presented no prognostic value with regard to OS in bladder cancer patients." (PMID 29861872, 2018). "In this meta-analysis, 11 out of the 13 included studies analyzed the role of TAMs in bladder cancer with CD68 marker, in combination with or without CD163 marker." (PMID 29861872, 2018). "Because CD11b+/CD68+ TAM flocked near the lymphatic vessels and VEGFR-3 was highly expressed in the lymphatic vascular endothelial cells, TAM could assist tumor-induced lymphangiogenesis by paracrine secretion of VEGF-C/D in bladder cancer." (PMID 21481239, 2011).
Hodgkins lymphoma (13 papers, 2012 to 2024). A heterogeneous group of malignant lymphoid neoplasms of B-cell origin characterized histologically by the presence of Hodgkin and Reed-Sternberg (HRS) cells in the vast majority of cases. "An increased number of CD68+ (a typical mark of TAMs) macrophages was strongly associated with shortened survival in patients with classic Hodgkin’s lymphoma, suggesting a new biomarker for risk stratification." (PMID 29892301, 2018). "Another recent, elegant study in Hodgkin's lymphoma provided a detailed mapping of distances between tumor associated macrophages, labeled with CD68 and CD4+/CD8+ T cells." (PMID 30619287, 2018). "CD68 is an important prognostic marker in Hodgkin lymphomas and it is correlated to the poor prognosis." (PMID 37345141, 2023). "We examined 44 cases of CHL, mostly nodular sclerosis subtype, in which the immunohistochemical stains for the histiocytic markers CD68 and CD163 were performed." (PMID 22289504, 2012). "We tested 44 cases of classical Hodgkin lymphoma for antibodies to both CD68 and CD163 to determine if CD163 may be a better macrophage marker to enumerate tumor associated macrophages in classical Hodgkin lymphoma." (PMID 22289504, 2012). "We do acknowledge there is generally not an ideal marker for the tissue identification of subsets of macrophages, however, as compared with the commonly used antibody to CD68 (KP-1), CD163 appears to be a better marker for enumeration of tumor associated macrophages classical Hodgkin lymphoma." (PMID 22289504, 2012). "A clinical trial of a chemotherapy regimen for advanced classical Hodgkin’s lymphoma demonstrated that an increase in CD68+ macrophages in the TME post-treatment was closely associated with poor prognosis, and CD68 could even be applied as a poor prognostic marker." (PMID 38787372, 2024). "After analyzing 44 cases of classical Hodgkin lymphoma, CD163 showed lower staining levels than CD68 in HRS rich areas." (PMID 22289504, 2012). "We used immunohistochemical staining for the macrophage/monocyte markers CD68 and CD163 to directly compare the staining characteristics in 44 cases of classical Hodgkin lymphoma." (PMID 22289504, 2012). "Triple immunofluorescent labelling for PD-1, PD-L1 and CD68 in tissues both of Hodgkin lymphoma and AITL revealed that CD68, marker for macrophage lineage, including monocytes and histiocytes, was solely and exclusively expressed in PD-L1+ cells and never in PD-1+ cells." (PMID 32143684, 2020). "In the case of classical Hodgkin lymphoma, there is a myriad of inflammatory and stromal elements surrounding the relatively few neoplastic cells, and high background staining can complicate matters when using the non-specific immunostain CD68." (PMID 22289504, 2012). "However, an increased number of TAMs, particularly CD68+ macrophages, was correlated with an increased likelihood of relapse after autologous hematopoietic stem-cell transplantation (P = 0.008) and shortened PFS (p = 0.03) in patients with classic Hodgkin’s lymphoma (HL)." (PMID 36578079, 2022).
prostate tumor (13 papers, 2012 to 2024). "Macrophages are an important component of all prostate tumors; their presence is associated with cancer progression and clinical outcomes depending on their phenotype (either cytotoxic-M1 (CD68) or protumorigenic-M2 (CD163))." (PMID 37444476, 2023). "Justified by the enrichment of CD68-positive macrophages detected by IHC in PTEN-deficient prostate tumors, we assessed how exposure to IR modulated TNF-α secretion from THP-1 cells." (PMID 26799286, 2016). "Also, S100A9 expression was observed in association with CD68+ macrophages in biopsies from human prostate tumors." (PMID 22470535, 2012). "A preclinical study found systemic carlumab administration repressed prostate tumor growth, reducing CD68+ macrophage infiltration and tumor microvascular density following monotherapy." (PMID 39076996, 2024). "For example, researchers found that ipilimumab therapy significantly increased VISTA expression on CD4 T cells, CD8 T cells, and CD68+ macrophages from matched pre- and post-treatment prostate tumors." (PMID 36389756, 2022). "The expression of S100A9 was related to the expression of CD68 macrophages in a human prostate tumor biopsy." (PMID 33912559, 2021). "To quantify these differences in tissue distributions of CD68+ macrophages, we again applied the histological image and size distribution analysis algorithms to the CD68-stained whole prostate tumor, liver, and spleen cross-sections." (PMID 28912459, 2017). "In line with this we here show that, intra-prostatic tumors gave rise to an increased density of CD68 + macrophages in the liver, presumably activated Kupffer cells and recruited macrophages, suggesting that circulating factors could be involved in tumor-induced liver alterations also in our model." (PMID 35551231, 2022). "We observed PGCC co-expressing macrophage (CD68 or macrophage-panel) markers and PSMA, possibly derived by the fusion of a macrophage cell with a prostate tumor cell." (PMID 37444476, 2023). "Immunohistochemical analyses were performed to identify CD209+ (immature DC), CD83+ (mature DC), CD68+ (total MΦ) and CD163+ (M2-type MΦ) cells in the 99 prostate tumors." (PMID 37435060, 2023). "Abundant immune cells have been detected in prostate tumor tissues by immunohistochemistry using different markers (CD3+, CD8+, CD20+, CD56+, CD68+ and Foxp3+)." (PMID 27368058, 2016). "We have previously shown that S100A9 expression is detected in CD68 positive macrophages in the prostate tumor stroma and in the non-malignant prostate stroma adjacent to prostate tumors, suggesting monocytes/macrophages as a plausible source of S100A9 also in tumors." (PMID 34067757, 2021). "Notably, markers of chronic inflammation, such as CD3 receptors or CD68, are strongly correlated with NKX3.1 status in human prostate tumors, which is not the case for markers of acute inflammation such as CEACAM8 or CD177." (PMID 30266798, 2018).